XPO1 (exportin 1)
Diseases named in the same sentence as XPO1 in open-access papers (continued):
Sharing a sentence is not in itself a finding about the gene and the disease.
tumor (continued). "Positive staining for XPO1, RPL12, RPS16, and pS6 proteins was also observed in both primary prostate and lung metastatic tumor cells developed in castrated TripleTg mice." (PMID 38336745, 2024). "The suppression of XPO1 expression by KPT‐330 triggers the nuclear relocation of FOXO1 and HMGB1, thereby overcoming platinum resistance in tumour cells." (PMID 38783482, 2024). "XPO1 protein levels are elevated, among others, in PDAC (pancreatic ductal adenocarcinoma), which plays a role in blocking TSP (tumor-suppressing protein) function through constant nuclear export." (PMID 39459201, 2024). "Exportin 1 (XPO1) plays an important role in the nuclear export of over 200 proteins, many of which are tumor suppressor." (PMID 39606156, 2024). "The combination of XPO1 inhibitor KPT-8602 and sorafenib has a better tumor treatment effect than sorafenib alone." (PMID 38835670, 2024). "We observed that the expression levels of XPO1 and RCN2 were elevated in tumor tissues compared with adjacent-tumor tissues." (PMID 39712016, 2024). "Inhibiting Exportin-1 (XPO1) in vivo induces marked tumor regression in an autochthonous MYC-transgenic HCC model and inhibits tumor growth in HCC patient-derived xenografts." (PMID 38302473, 2024). "For each type of analyzed tumour type, we selected TARGET genes showing a statistically significant correlation with XPO1 (p ≤ 0.05) with Pearson’s correlation indexes R > 0.2 or R < −0.2." (PMID 37046649, 2023). "Given the multitude of pathways regulated by XPO1, it is critical to take a broader approach for understanding the impact of nuclear export inhibition on PDAC tumour and microenvironment supporting pathways." (PMID 38131168, 2023). "Combined use of XPO1 and BCL2 inhibitors can synergistically induce the apoptosis of DHL tumor cells in vitro, and most importantly, block tumor progression and spread in vivo." (PMID 35303910, 2022). "XPO1 (chromosome region maintenance 1 or CRM1) mediates the nuclear export of several proteins, mainly tumor suppressors." (PMID 36180918, 2022). "Taken together, these results suggested that the XPO1 inhibitor, KPT-330, inhibited tumor growth in vivo with a good safety profile." (PMID 36180918, 2022). "Gravina and others used a selective inhibition of XPO1, Selinexor (KPT-330), to demonstrate that XPO1 inhibition affects the metastatic potential of PCa cells using one model of intraprostatic tumor growth and two models of bone metastasis." (PMID 34858485, 2021). "Bulk and single-cell RNA-sequencing, immunohistochemistry, and analysis of published genomic datasets found that XPO1 was abundantly expressed in human basal-like TNBC cell lines, PDXs, and patient tumor samples." (PMID 34628286, 2021). "We observed that a circular transcript of XPO1 (circBase ID: hsa_circ_0001016, denoted “circXPO1” in this study) is highly expressed in LUAD tissues compared with adjacent non-tumor tissues." (PMID 33268793, 2020). "Interestingly, XPO1 inhibition might also affect the tumor microenvironment with antitumor effects." (PMID 32624581, 2020). "XPO1 and BCL2 inhibitors synergize in vitro to induce apoptosis in DHL tumor cells, and most importantly, block tumor progression and dissemination in vivo." (PMID 31752970, 2019). "Exportin-1 (XPO1), which is a member of the importin-β superfamily of karyopherins, is the major exporter of many tumor suppressor proteins that are involved in the progression of PAC." (PMID 31052304, 2019). "Co-targeting XPO1 and ERα in endocrine resistant tumors resensitizes tumors to TAM and achieve complete tumor regression by inhibiting cell metabolism and inducing autophagy." (PMID 30987380, 2019).
tumor (continued). "XPO1 overexpression was observed in 52.5% of CRC and significantly apparent with strong intensity in tumor cells compared to the normal adjacent epithelium (P<0.001)." (PMID 31870117, 2019). "Here, we demonstrate that XPO1 inhibition abrogates MYC protein expression and induces massive tumor cell apoptosis." (PMID 31752970, 2019). "Both XPO1 and PAK4 inhibitors, when combined with lenvatinib, showed superior anti-tumor activity in 8505C sub-cutaneous xenograft." (PMID 31905765, 2019). "The combined targeting of ERα and XPO1 overcame TAM resistance, modulated cellular signaling to prevent rewiring of tumor cell metabolism and induced cell death by autophagy." (PMID 30987380, 2019). "Most importantly, combination therapy with XPO1 and BCL2 inhibitors blocks tumor progression and metastasis and extends survival in a mouse model bearing patient-derived DHL tumors." (PMID 31752970, 2019). "We concluded that XPO1 suppression abrogates the function of MYC oncogene and induces mass apoptosis in DHL tumor cells." (PMID 31752970, 2019). "Combination therapy with XPO1 inhibitors, especially KPT-330, and conventional chemotherapeutic agents has shown promising synergistic effects in a variety of human tumor types." (PMID 30143046, 2018). "Exportin 1 (XPO1) is a known mediator of the nuclear export of more than 200 proteins, many of which have tumor suppressor functions." (PMID 29220294, 2018). "In order to investigate the effects of XPO1 signaling on the expression of miRNAs, we transfected XPO1 siRNA into PDAC cells and tested the expression level of several tumor suppressive miRNAs." (PMID 29137251, 2017). "Exportin-1 (XPO1, CRM1) is a crucial protein involved in the nuclear export of many cellular proteins, including various tumor suppressive and growth regulatory proteins." (PMID 27634897, 2016). "Consistently with previous works in different tumor type models, immunoblotting analysis revealed that nuclear XPO1/CRM1 expression progressively decreased after SINE treatment." (PMID 25948791, 2015). "We have previously demonstrated that the inhibition of XPO1 with SINE reduced the cell and tumor growth in PCa preclinical models inducing G2/M cell cycle accumulation and apoptosis." (PMID 25284315, 2014). "Taken together, both human and canine DLBCL express XPO1 and SINE compounds show potent activity against these tumor cells, suggesting a potential therapeutic benefit for human and canine patients with DLBCL." (PMID 24503695, 2014). "A well-known natural product XPO1-specific inhibitor, Leptomycin, LMB, possesses strong anti-tumor activity in vitro, but phase I trials of LMB were discontinued because of its toxicity and lack of apparent efficacy in the tolerable dose range." (PMID 25284315, 2014). "XPO1 protein expression was correlated with increased serum level of CEA, more advanced tumor stages, positive Her2 status, and distant metastasis." (PMID 25476752, 2014). "An oral small molecule reversible inhibitor of XPO1, CBS9106 induced cell cycle arrest and apoptosis in 60 different human tumor cell lines and suppressed tumor growth in mouse xenografts without any significant morbidity or mortality." (PMID 24503695, 2014). "Additionally, XPO1+ Epithelial can promote angiogenesis via VEGFA-VEGFR1/R2, thereby facilitating tumor growth, which aligns with our previous study." (PMID 39712016, 2024).
tumor (continued). "XPO1 exhibited significant exon skip alterations in tumors compared to adjacent normal samples, while the alternative 3’ change of EEF1B2 showed a significant difference between tumor and adjacent normal samples." (PMID 37735421, 2023). "The cytotoxic effects of compound 1l in HGC27 and MGC803 gastric cancer cell lines have been investigated; compound 1l was reported to degrade XPO1, inducing apoptosis in both MGC803 and HGC27 cell lines, exhibiting strong cytotoxic and anti-tumour effects against these cells." (PMID 38938904, 2022). "In addition, the expression levels of KRAS, XPO1, ERK2 and BCL-2 mRNA were found to be significantly decreased in the residual tumor samples from the combination group." (PMID 35573474, 2022). "We therefore hypothesize that tumor cells with concurrent MYC and BCL2 overexpression, such as DHL, may be effectively targeted through the combined treatment with XPO1 and BCL2 inhibitors." (PMID 31752970, 2019). "Furthermore, combined suppression of XPO1 and BCL2 synergizes to induce massive cell death in DHL tumor cells in vitro." (PMID 31752970, 2019). "Additional low-frequency SNVs in KDM6A (in-frame gain of codon, allelic frequency 7%) and XPO1 (splice region variant, allelic frequency 6%) were identified in the PDOX, but not in the patient tumor or the subcutaneous PDX." (PMID 31732509, 2019). "Collectively, these results may add insights of XPO1 involvement in the CRC pathogenesis and progression leading to poorly differentiated tumors and advance tumor stages." (PMID 31870117, 2019). "However, to our surprise, none of the DHL cell lines was resistant to both, lending experimental support to the combinatorial use of XPO1 and BCL2 inhibitors to eradicate DHL tumor cells." (PMID 31752970, 2019). "Further, XPO1 RNAi could suppress spheroid formation in vitro and also suppress the growth of CSC-derived tumor xenograft." (PMID 29735942, 2018). "Given its significance in regulating the expression of so many critical tumor suppressors and genome surveillance proteins, it is not surprising to note that XPO1 is found to be over-expressed in several different tumor types." (PMID 29735942, 2018). "To identify the sub-population of TNBC patients who may potentially benefit from treatment with selinexor, we assessed the levels of ARRDC3, XPO1 and ITG β4 from normal biopsy tissue as well as in 114 biopsies of TNBC patient tumor samples." (PMID 28881784, 2017). "As survivin requires XPO-1/XPO1-RanGTP for its nuclear exit, inhibiting the activity of this complex could directly address this therapeutic need by increasing the tumor-suppressive nuclear survivin and reducing the antiapoptotic cytoplasmic survivin." (PMID 26620414, 2015). "It is recognized that XPO1 is the major exporter of many nuclear cargoes and not all have tumor suppressor function." (PMID 26536918, 2015). "KPT185-trans isomer (which has ∼100 fold less XPO1 inhibition activity as the cis-isomer), showed much less toxicity when it was tested using Jurkat cells and one of primary canine DLBCL samples (IC50 were >1000 nM in both tumor cells)." (PMID 24503695, 2014). "Chromosome Region Maintenance 1, or exportin-1 (CRM1/XPO1), is involved with the export of more than 200 nuclear proteins, and has intriguingly been shown to have an increased expression in several tumor cell types." (PMID 25281264, 2014).
tumor (continued). "Since XPO1 inhibition leads to the restoration of so many TSPs at once, it is theorized that anti-tumor activity can be independent of oncogenic drivers responsible for maintenance of the neoplastic phenotype." (PMID 24503695, 2014). "However, there are certain requirements for inclusion in clinical patients, for example, tumor tissue samples should have increased protein expression of KLF5, XPO1 and Cyclin D1, and no mutation of RB1 and positive expression in the cytoplasm." (PMID 39888288, 2025). "Blocking XPO1 leads to the activation of CD8+ T-lymphocytes and NK cells, M2 to M1 macrophage re-polarization, and the inhibition of myeloid-derived suppressor cells (MDSCs) and neutrophil extracellular traps, which provide potent immunosuppressive effects in the tumor microenvironment." (PMID 40565816, 2025). "Thus, short-term therapeutic inhibition of the nucleocytoplasmic transport gene, Xpo1, induces tumor regression without affecting normal adjacent liver in an autochthonous transgenic mouse model of MYC-induced HCC." (PMID 38302473, 2024). "Exportin 1 (XPO1), also referred to as chromosomal maintenance region 1 (CRM1), is a key nuclear transport receptor involved in the export of more than 200 known cargo proteins, including tumor suppressors, anti-inflammatory factors, and growth-regulating proteins." (PMID 35721113, 2022). "Of note, XPO1 and ERα expression were lost in the only tumor that we could detect in the TAM + 5 mg/kg SEL group after we stopped treatment, explaining recurrence in this particular tumor." (PMID 32847042, 2020). "Our previous studies identified Exportin 1 (XPO1), a nuclear export protein, as an important player in endocrine resistance progression and showed that combining selinexor (SEL), an FDA-approved XPO1 antagonist, synergized with endocrine agents and provided sustained tumor regression." (PMID 32847042, 2020). "Because PBMC could not be used as surrogate cell population to measure XPO1 occupancy by selinexor due to low target expression, instead the minimal amount of tumor cells required for reliable occupancy measurements was defined." (PMID 29299164, 2017). "In conclusion, the 3D nuclear telomere architecture of tumor cells is preferentially disrupted by XPO1 inhibition, while that of normal cells was minimally or not affected suggesting a tumor cell–specific effect of XPO1 inhibition on nuclear architecture." (PMID 26991404, 2016). "Additionally, XPO1 blockade reduces the translation of short-lived immune-suppressive proteins (e.g., PD-L1) and perturbs stress-adaptation circuits that drive immune checkpoint upregulation—effects that synergize with BH3 mimetics (venetoclax) and HMAs (azacitidine) to enhance anti-tumor immunity." (PMID 41347170, 2025). "Interestingly, the combination of XPO1 and tamoxifen blocked the activation of the AKT signalling pathway, induced autophagy, improved the treatment sensitivity to tamoxifen and reshaped the tumour metabolic pathway, which provided a new approach for the future treatment of breast cancer." (PMID 38783482, 2024). "Because XPO1 is upregulated in tumors and selinexor selectively blocks translation in tumor cells, a potential advantage for blocking NKG2A:HLA-E interactions via selinexor rather than antibodies is that selinexor may retain expression of HLA-E on non-tumor cells." (PMID 34926302, 2021). "Our data using a human tumor cell model and CLL patient cells with heterozygous XPO1-E571K expression support this claim, as we observed no change in proliferation potential between wt and E571K mutant cells upon treatment with these molecules." (PMID 33451349, 2021).
infection (53 papers, 2008 to 2026). The state of being infected such as from the introduction of a foreign agent such as serum, vaccine, antigenic substance or organism. "In this study, we have identified an essential role of XPO1 in regulating Kaposi’s sarcoma-associated herpesvirus (KSHV) lytic replication during primary infection of primary human umbilical vein endothelial cells." (PMID 33414399, 2021). "Of 29 trial patients with an XPO1 mutation, 17 (59%) died of infection, nine died of other causes and three survived." (PMID 33580200, 2021). "Notably, loss of XPO1 function in Arabidopsis and N. benthamiana significantly reduces TuMV replication and infection." (PMID 40636018, 2025). "NS1 has been demonstrated to have an immunomodulatory role during infection, and NEP has been implicated in the export of vRNPs from the nucleus via exportin-1 (XPO1)." (PMID 41576158, 2026). "We found that transcription of XPO1 mRNA level was slowly increased during TBSV replication up to 7-fold by the fifth day of infection." (PMID 40828816, 2025). "In patients with mutation data, the factors significantly associated with death from infection versus all other deaths were 11q deletion (47/162 [29%] versus 40/209 [19%], P = 0.03) and mutations of the BRAF, FBXW7, NRAS and XPO1 genes." (PMID 33580200, 2021). "Decrease in viral titre and change in plaque morphology indicate disruption of XPO1 function as a promising post-infection therapy against RSV." (PMID 34584169, 2021). "Multivariate analysis in these 400 patients showed that the factors most significantly associated with death from infection were 11q deletion and mutations of the BRAF, NRAS and XPO1 genes." (PMID 33580200, 2021). "At the late phase of the lytic infection cycle, pp65 utilizes XPO1-mediated transport to shuttle from the nucleus to the cytoplasm, and disruption of XPO1-medited export of pp65 by LMB results in its nuclear retention, and dampens viral replication." (PMID 34012430, 2021). "Here, we have identified a critical role of XPO1 in KSHV lytic replication during primary infection." (PMID 33414399, 2021). "The infection cycle of many viruses relies on XPO1 for transporting viral and cellular components from the nucleus to the cytoplasm." (PMID 34012430, 2021). "We used KPT-8602 to investigate XPO1’s role in KSHV primary infection in HUVEC as these cells support productive infection." (PMID 33414399, 2021). "Leptomycin B (LMB) has been shown to inhibit HCV by inhibiting nuclear export mediated by XPO1, and this inhibitory effect was lost at 8 h post infection." (PMID 25485706, 2014). "Plant cells might be able to detect the reduced availability of “free” XPO1 in the cytosol and/or the nucleus during infection." (PMID 40828816, 2025). "We evaluated the ability of the NRF2 activators 4-octyl itaconate (4OI), bardoxolone methyl (BARD), sulforaphane (SFN), and the inhibitor of exportin-1 (XPO1)-mediated nuclear export selinexor (SEL) to interfere with influenza virus A/Puerto Rico/8/1934 (H1N1) infection of human cells." (PMID 37459366, 2023). "Interestingly, M is localised to the nucleus early in infection and its export into the cytoplasm by the nuclear exporter, exportin-1 (XPO1) is essential for RSV assembly." (PMID 34584169, 2021). "Among the panel of 21 genes commonly mutated in CLL, univariate analysis showed that mutations of BRAF, FBXW7, NRAS and XPO1 were significantly associated with death from infection versus deaths not due to infection." (PMID 33580200, 2021). "Notably, the nuclear export of DDX3X via exportin-1 is critical for maximal gene induction, and thereby presumably results in a more effective innate and adaptive immune response to infection, and as demonstrated in our hPIV-3 infectious model." (PMID 31575075, 2019).